PRR19 (proline rich 19)
Description:
Promotes meiotic crossing over formation through its interaction with CNTD1 by participating in the crossover differentiation step of crossover-specific recombination intermediates.
Synonyms: MGC70924
Tractability: No criterion of Open Targets' tractability assessment is met for any kind of drug.
Gene: Protein-coding gene on chromosome 19 (42,302,098 to 42,310,814, forward strand). Ensembl gene ENSG00000188368.
Subcellular location: Nucleus; Chromosome
Subcellular location (Human Protein Atlas): Mitotic chromosome; Nucleoli; Nucleoli rim; Mitochondria; Nuclear bodies; Nucleoplasm
Gene Ontology:
Molecular function: protein binding
Cellular component: chromosome; nucleus
Genetic constraint (gnomAD): Loss-of-function variants: 9 observed, 19.44 expected, observed/expected ratio (o/e) 0.46, 90% interval 0.28 to 0.81. The upper end of that interval is the gene's LOEUF score, 0.81, which puts it in group 3 of 6, group 1 being the genes least tolerant of losing a copy. Missense variants: 454 observed, 480 expected, observed/expected ratio (o/e) 0.95, 90% interval 0.88 to 1.02. Synonymous variants: 188 observed, 196.63 expected, observed/expected ratio (o/e) 0.96, 90% interval 0.85 to 1.08.
Homologues: Orthologues: chimpanzee PRR19 (99% identical), macaque PRR19 (96% identical), rabbit PRR19 (80% identical), dog PRR19 (78% identical), guinea pig PRR19 (76% identical), pig PRR19 (74% identical), rat Prr19 (71% identical), mouse Prr19 (70% identical).
Diseases named in the same sentence as PRR19 in open-access papers:
PRR19 is named in the same sentence as 2 diseases in open-access papers, as found by Europe PMC text mining. Sharing a sentence is not in itself a finding about the gene and the disease. The quoted sentences say what the papers report.
hearing-loss (1 paper, 2025). "The protein–protein interaction network analysis identified prominent interaction characteristics among neighboring genes of tinnitus-associated loci (RUNX2, TGFB2, CDH1, and DEFB family) and hearing-loss-associated loci (CDH1, PRR19, and MAGOHB)." (PMID 40362371, 2025).
PRR19 also shares sentences with these, for which no sentence is quoted: Tinnitus (1 paper).